CHRNA9 (cholinergic receptor nicotinic alpha 9 subunit)
Description:
Component of neuronal acetylcholine receptors (nAChRs) that function as pentameric, ligand-gated cation channels with high calcium permeability among other activities. nAChRs are excitatory neurotrasnmitter receptors formed by a collection of nAChR subunits known to mediate synaptic transmission in the nervous system and the neuromuscular junction. Each nAchR subunit confers differential attributes to channel properties, including activation, deactivation and desensitization kinetics, pH sensitivity, cation permeability, and binding to allosteric modulators. Forms either homopentamers or heteropentamers with CHRNA10. Expressed in the inner ear, in sympathetic neurons and in other non-neuronal cells, such as skin keratinocytes and lymphocytes. nAChR formed by CHRNA9:CHRNA10 mediate central nervous system control of auditory and vestibular sensory processing. The channel is permeable to a range of divalent cations including calcium, the influx of which may activate a potassium current which hyperpolarizes the cell membrane. In the ear, mediates synaptic transmission between efferent olivocochlear fibers and hair cells of the cochlea, this may lead to a reduction in basilar membrane motion, altering the activity of auditory nerve fibers and reducing the range of dynamic hearing. This may protect against acoustic trauma (By similarity). May also regulate keratinocyte adhesion.
Synonyms: NACHRA9; HSA243342
Tractability: Small molecule: a drug acting on it is in phase 2 or 3 trials; a structure with a bound ligand is known; a high-quality ligand is known; it belongs to a druggable protein family. Antibody: UniProt places it where antibodies can reach, with high confidence; its Gene Ontology location is reachable by antibodies, with high confidence; UniProt predicts a signal peptide or a membrane-spanning region. PROTAC: ubiquitination databases record sites on it; a small molecule that binds it is known.
Target class: Ion channel; Nicotinic acetylcholine receptor alpha subunit; Ligand-gated ion channel; Nicotinic acetylcholine receptor
Gene: Protein-coding gene on chromosome 4 (40,335,333 to 40,355,217, forward strand). Ensembl gene ENSG00000174343.
Subcellular location: Synaptic cell membrane; Cell membrane
Pathways (Reactome):
Neuronal System: Highly calcium permeable postsynaptic nicotinic acetylcholine receptors
Sensory Perception: Acetylcholine inhibits contraction of outer hair cells
Gene Ontology:
Molecular function: acetylcholine-gated monoatomic cation-selective channel activity; protein binding; neurotransmitter receptor activity; extracellular ligand-gated monoatomic ion channel activity; monoatomic ion channel activity; transmembrane signaling receptor activity; transmitter-gated monoatomic ion channel activity involved in regulation of postsynaptic membrane potential
Biological process: acetylcholine receptor signaling pathway; positive regulation of cytosolic calcium ion concentration; calcium ion transport; monoatomic ion transmembrane transport; regulation of membrane potential; synaptic transmission, cholinergic; chemical synaptic transmission, postsynaptic; excitatory postsynaptic potential; membrane depolarization; monoatomic ion transport; negative regulation of ERK1 and ERK2 cascade; regulation of postsynaptic membrane potential; response to auditory stimulus
Cellular component: acetylcholine-gated channel complex; plasma membrane; neuron projection; synapse; transmembrane transporter complex; cholinergic synapse; membrane; postsynaptic membrane; postsynaptic specialization membrane; synaptic membrane
Genetic constraint (gnomAD): Loss-of-function variants: 21 observed, 34.28 expected, observed/expected ratio (o/e) 0.61, 90% interval 0.43 to 0.88. The upper end of that interval is the gene's LOEUF score, 0.88, which puts it in group 3 of 6, group 1 being the genes least tolerant of losing a copy. Missense variants: 579 observed, 598.1 expected, observed/expected ratio (o/e) 0.97, 90% interval 0.9 to 1.04. Synonymous variants: 223 observed, 234.4 expected, observed/expected ratio (o/e) 0.95, 90% interval 0.85 to 1.06.
Homologues: Orthologues: chimpanzee CHRNA9 (99% identical), macaque CHRNA9 (98% identical), dog CHRNA9 (96% identical), rabbit CHRNA9 (93% identical), pig CHRNA9 (92% identical), rat Chrna9 (91% identical), mouse Chrna9 (91% identical), guinea pig CHRNA9 (89% identical), tropical clawed frog chrna9 (70% identical), zebrafish chrna9a (65% identical), zebrafish chrna9b (64% identical). Paralogues in human: CHRNA10 (52% identical), CHRNA7 (36% identical), CHRNA4 (34% identical), CHRNA6 (33% identical), CHRNA1 (33% identical), CHRNA2 (33% identical), CHRNA3 (33% identical), CHRNA5 (31% identical), CHRNB4 (30% identical), CHRNB3 (30% identical), CHRNB2 (30% identical), CHRFAM7A (29% identical), and 33 more.
Diseases named in the same sentence as CHRNA9 in open-access papers:
CHRNA9 is named in the same sentence as 30 diseases in open-access papers, as found by Europe PMC text mining. Sharing a sentence is not in itself a finding about the gene and the disease. The quoted sentences say what the papers report.
breast carcinoma (9 papers, 2017 to 2024). "In a case–control study, it was found that an increased risk of breast cancer was associated with the variant rs73229797 allele on the CHRNA9 gene." (PMID 38921563, 2024). "The expression of CHRNA9 is specifically increased in breast cancer, and down-regulation of CHRNA9 expression can cause the growth cycle arrest of breast cancer cells, affect cell proliferation and migration, and inhibit the growth of cancer cells." (PMID 38495483, 2024). "It found that an increased risk of breast cancer is associated with the variant rs73229797 allele on the CHRNA9 gene, and that the risk is greater in both active and passive smokers." (PMID 35126059, 2021). "In contrast with several above-mentioned MPs (e.g., CD44, EGFR/ERBB2, and APP) that have been well studied, the interacting partners and pathways associated with CHRNA9 in breast cancer remain to be elucidated." (PMID 31311925, 2019). "Variation within CHRNA9 region was associated with increased breast cancer risk and non-small cell lung cancer risk." (PMID 28521825, 2017). "One case-control study of 737 breast cancer patients and 719 age-matched healthy controls has studied the association between CHRNA9 SNPs and the risk of breast cancer, and examined the joint effect of cigarette smoke exposure and CHRNA9 SNPs on developing breast cancer." (PMID 35126059, 2021). "CHRNA9 has been shown to inhibit the proliferation of lung and breast cancer cells to alleviate disease progression." (PMID 38495483, 2024). "As the short-range Chrna9 gene promoter was analyzed in breast cancer and neuroblastoma cell lines, the detailed regulatory mechanisms and functional role of α9-nAChR in iTreg cells and other T-cell subsets deserve further investigation." (PMID 35163704, 2022). "Next, we observed high protein expression of CHRNA9 and ERBB2, having an SSIM = 3.66 and displaying a strong association, in HER2-enriched breast cancer cell lines (e.g., BT474) compared with that in the other cell lines." (PMID 31311925, 2019). "Next, we investigated the generalizability of CRISPR/Cas9 genome editing in breast cancer cells by targeting selected protospacers on the CHRNA9 DNA locus." (PMID 29163048, 2017). "Our findings also indicated a role for CHRNA9 in breast cancer metastasis." (PMID 31311925, 2019). "In subsequent experiments, we validated whether CHRNA9 and ERBB2 could form a complex by using nicotine as an agonist for CHRNA9 and investigating downstream signaling in breast cancer cells." (PMID 31311925, 2019). "Moreover, the knockdown of CHRNA9 blocked the growth of human breast cancer cells." (PMID 38921563, 2024). "For example, we identify CHRNA9 with 12 PPIs (e.g., ERBB2) can be a therapeutic target and find its anti-metastasis agent, bupropion, for treatment in nicotine-induced breast cancer." (PMID 31311925, 2019).
glioma (3 papers, 2016 to 2024). A benign or malignant brain and spinal cord tumor that arises from glial cells (astrocytes, oligodendrocytes, ependymal cells). "CHRNA9 was also found to be abnormally expressed in various other tumors and associated with the expression levels of numerous immune checkpoints in glioma." (PMID 38495483, 2024). "The potential association between CHRNA9 and the clinicopathological features of glioma patients was also investigated." (PMID 38495483, 2024). "We identified CHRNA1 and CHRNA9, two alpha subunits of the AChR complex, to be upregulated in glioma with strong association between expression and patient survival." (PMID 26575950, 2016). "CHRNA9 is also differentially expressed between tumor tissues and normal tissues in various cancer types and is associated with various immune cell abundance and immune checkpoints in glioma." (PMID 38495483, 2024). "More importantly, the correlation between CHRNA9 and the expression levels of most immune checkpoints in glioma is statistically significant." (PMID 38495483, 2024). "The correlation between the expression level of CHRNA9 and the prognosis of glioma was analyzed by Cox regression." (PMID 38495483, 2024). "The abundance levels of most immune cells in glioma tissues are correlated with the expression levels of CHRNA9 (P <0.05)." (PMID 38495483, 2024). "We collected glioma and paracancerous samples from clinical patients and found that the mRNA expression level and protein expression level of CHRNA9 increased in glioma samples." (PMID 38495483, 2024). "The RT-qPCR results showed that compared with the para-cancer tissues, the mRNA expression level of CHRNA9 in the glioma samples was increased, and the difference was statistically significant (P < 0.01)." (PMID 38495483, 2024). "Based on the median expression of CHRNA9 and the relevant clinical characteristics of glioma samples, glioma samples were divided into CHRNA9 high-expression and low-expression groups." (PMID 38495483, 2024). "According to the author's cell annotation criteria and results, single-cell sequencing showed that CHRNA9 was highly expressed in glioma cells, but relatively low in myeloid cells, T cells, and B cells." (PMID 38495483, 2024). "The mRNA expression level of CHRNA9 in glioma tissues was higher than that in paracancerous tissues found by RT-qPCR detection." (PMID 38495483, 2024). "The findings from the analysis of clinical samples revealed that the expression levels of both mRNA and protein of CHRNA9 in glioma tissues were higher than those in paracancerous tissues." (PMID 38495483, 2024). "In our study, the expression of CHRNA9 and its primary mechanism of action in glioma were analyzed and predicted by bioinformatics methods." (PMID 38495483, 2024). "The aim of this study was to verify the expression level of CHRNA9 in glioma and its effect on prognosis by bioinformatics methods." (PMID 38495483, 2024). "In this study, the glioma samples in the TCGA database were divided into high expression group and low expression group according to the expression level of CHRNA9 by bioinformatics method." (PMID 38495483, 2024). "Although there is no relevant literature reporting the specific mechanism of CHRNA9 and immune cells, in our study we found that the expression level of CHRNA9 in glioma is correlated with the enrichment of most immune cells." (PMID 38495483, 2024). "The Kaplan-Meier method and Cox regression were utilized to analyze the relationship between CHRNA9 expression level and survival time and prognostic value of glioma patients." (PMID 38495483, 2024). "Taken together, our study confirmed that CHRNA9 expression was increased in glioma, CHRNA9 overexpression was considered to be an independent factor for poor prognosis in glioma patients." (PMID 38495483, 2024).
glioma (continued). "Based on the median expression value of CHRNA9 in glioma samples in the TCGA database, they were divided into high expression group and low expression group, and the expression difference analysis results between the two groups were shown in the volcano plot." (PMID 38495483, 2024). "Compared with the complete response-partial response (CR&PR) group, the expression level of CHRNA9 was increased in the stable disease-progressive disease (SD&PD) group of glioma samples (P < 0.001)." (PMID 38495483, 2024). "In our study, the results of bioinformatics analysis by mining the transcriptome data of glioma samples in the TCGA database showed that the expression level of CHRNA9 was higher than that of the normal group." (PMID 38495483, 2024). "To investigate the clinical importance of nAChRs in gliomas, we examined clinical outcomes and found that glioma patients with tumors overexpressing CHRNA1 or CHRNA9 (encoding for the AChR-α1 or AChR-α9) exhibit significant shorter overall survival." (PMID 26575950, 2016). "In gliomas, CHRNA9 is correlated with expression levels at most immune checkpoints." (PMID 38495483, 2024). "Although the significant roles of CHRNA9 in the disease progression of various tumors have been identified, its expression and mechanism of action in glioma remains unclear." (PMID 38495483, 2024). "Regulating the expression level of CHRNA9 may alleviate the level of immune infiltration in glioma tissue." (PMID 38495483, 2024). "Similarly, the protein expression level of CHRNA9 in glioma tissues was significantly higher than that in paracancerous tissues." (PMID 38495483, 2024). "Clinical glioma and para-cancer tissue samples are used to detect the expression level of CHRNA9." (PMID 38495483, 2024). "In this study, bioinformatics methods were used to analyze the clinically relevant information of glioma samples in the TCGA database, it was found that the expression level of CHRNA9 was correlated with the patients' WHO grade, IDH status, 1p/19q codeletion, Primary therapy outcome, and Age." (PMID 38495483, 2024). "The results of univariate Cox regression analysis showed that the high expression of CHRNA9 (P < 0.001), WHO grade (P < 0.001), IDH status (P < 0.001), Age (P < 0.001), Primary therapy outcome (P < 0.001), and 1p/19q codeletion (P < 0.001) were all associated with poor prognosis of glioma." (PMID 38495483, 2024). "This analysis revealed that survival of patients with tumors overexpressing CHRNA1 or CHRNA9, which are both expressed in all our GSC lines, is significantly shorter as compared to all gliomas (n = 343)." (PMID 26575950, 2016). "Pathway enrichment analysis based on DEGs between the two groups illustrated that there may be a regulatory relationship between CHRNA9 and the JAK/STAT signaling pathway during the progression of glioma disease, and CHRNA9 has been shown to activate STAT329." (PMID 38495483, 2024). "However, the correlation between the expression level of CHRNA9 in glioma and the clinical features and prognosis of glioma patients has not been clarified." (PMID 38495483, 2024). "CHRNA9 may intervene in the progression of glioma disease through the JAK/STAT pathway, and it may be a potential therapeutic target and prognostic biomarker for glioma." (PMID 38495483, 2024).
melanoma (3 papers, 2021 to 2023). A malignant, usually aggressive tumor composed of atypical, neoplastic melanocytes. "It was reported in melanoma cells that stimulation of Chrna9 with nicotine activates AKT43." (PMID 36709241, 2023). "In melanoma, it has been shown that nicotine could induce PD-L1 expression via CHRNA9 and could promote cell proliferation and migration." (PMID 34771509, 2021).
non-small cell lung carcinoma (3 papers, 2017 to 2020). A group of at least three distinct histological types of lung cancer, including non-small cell squamous cell carcinoma, adenocarcinoma, and large cell carcinoma. "Some scholars also concluded that CHRNA9 was similarly overexpressed in HNSC, and the expression of CHRNA6 was significantly higher in molecular features of non-small cell lung cancer." (PMID 33304845, 2020).
Graves disease (2 papers, 2014). Graves' disease is an autoimmune disorder that leads to overactivity of the thyroid gland (hyperthyroidism).It is caused by an abnormal immune system response that causes the thyroid gland to produce too much thyroid hormones. "RHOH/CHRNA9 rs6832151, previously associated with Grave's Disease, generalized to serum TSH levels in African Americans (p = 0.01, β = −0.10)." (PMID 25436638, 2014).
lung carcinoma (2 papers, 2011 to 2019). "The biologic activities of α9 nAChR may be regulated at the splicing level, and genetic polymorphisms in CHRNA9 affecting protein levels, amino acid sequence and RNA splicing may influence the risk for lung cancer." (PMID 22125646, 2011). "Elucidation of the mechanisms, by which individual genetic variations in CHRNA9 affecting its expression, protein structure, and RNA splicing influence predisposition to lung cancer may lead to the development of personalized approaches to cancer prevention and treatment." (PMID 22125646, 2011). "Similarly, the inhibitory effect of the CHRNA9/ERBB2 complex disassociation and signal transduction caused by bupropion were also found in lung cancer (A549) cells exposed to nicotine." (PMID 31311925, 2019).
neuroblastoma (2 papers, 2022 to 2023). Neuroblastoma (NB) is the most common solid, extracranial childhood tumor. "In addition, it was reported in human CHRNA9 gene that activation and repression elements in the 5′-nonconding region play important roles for transcriptional regulation in CHRNA9-expressing human neuroblastoma SH-SY5Y cells." (PMID 36709241, 2023).
acute myocardial infarction (1 paper, 2023). Necrosis of the myocardium, as a result of interruption of the blood supply to the area. "However, there is evidence GPM6A and CHRNA9 may be involved in myocardial development and repair and GPM6A is differentially expressed with respect to acute myocardial infarction." (PMID 37533055, 2023).
alcohol dependence (1 paper, 2023). Physical and psychological dependence on alcohol. "Among the genes identified include those previously reported for nicotine and alcohol dependence (CHRNA9 and CRHBP)." (PMID 37915799, 2023).
deafness (1 paper, 2022). An inherited or acquired condition characterized by the complete loss of the ability to hear from one or both ears. "Cholinergic receptor nicotinic alpha 9 subunit (α9 nAChR) is predominantly expressed in the outer hair cells of the cochlea, which plays a critical role in the regulation of the proteins of deafness genes." (PMID 36284268, 2022).
diabetes (1 paper, 2023). "While diabetes has been linked to aberrant calcium signaling, GPM6A and CHRNA9 have not previously been specifically implicated in contributing to CVD risk in diabetes." (PMID 37533055, 2023).
drug dependence (1 paper, 2023). "CHRNA9 is of interest because of previous reports of its association with AUD, nicotine dependence, and drug dependence." (PMID 37915799, 2023).
hepatitis B (1 paper, 2019). "For instance, our results indicate that the CHRNA9 community was suggested to be implicated in the hepatitis B pathway in five cancers, such as liver hepatocellular carcinoma (LIHC; pink) and KIRC (light blue)." (PMID 31311925, 2019).
triple-negative breast carcinoma (1 paper, 2019). An invasive breast carcinoma which is negative for expression of estrogen receptor (ER), progesterone receptor (PR), and human epidermal growth factor receptor 2 (HER2). "Furthermore, a clinical investigation of HER2+ breast tissues revealed a strong protein interaction between CHRNA9 and ERBB2 compared to that in triple-negative breast cancer (TNBC) breast tissues." (PMID 31311925, 2019).
type 1 diabetes (1 paper, 2023). "Importantly, our findings suggest epigenetic modification of GPM6A and CHRNA9, both involved in calcium channel activity and development, may play a role in the pathophysiology of CVD under conditions of higher glycemic exposure in type 1 diabetes." (PMID 37533055, 2023).